IDH2 (isocitrate dehydrogenase (NADP(+)) 2)
Diseases named in the same sentence as IDH2 in open-access papers (continued):
Sharing a sentence is not in itself a finding about the gene and the disease.
cancer (continued). "Associations among the structure, function and stability of IDH2 mutants have rarely been reported, and these parameters are closely related to the occurrence and proliferation of cancer." (PMID 36335201, 2022). "Mutations in IDH2 have been observed in several human cancers, especially in low-grade gliomas and AML patients." (PMID 35313945, 2022). "IDH2 mutated carcinomas presented other distinctive molecular features including a global methylation phenotype and an increase in repressive trimethylation of H3K27 in comparison to IDH2 wild-type tumors." (PMID 35326613, 2022). "Given the importance of these genes, we investigated the IDH1 and IDH2 mutations in a large series of cancer cases (n = 14,726) (solid malignancies) from the data of The Cancer Genome Atlas and the Memorial Slone Kettering Cancer Centre." (PMID 35996504, 2021). "Through a survey of more than 45,000 pan-cancer samples, we observed that IDH1 and IDH2 hotspot mutations are uncommon (2%) and extremely rare (0.4%), respectively, in human cancer, a finding in agreement with an independent pan-cancer analysis." (PMID 34440884, 2021). "IDH1 and IDH2 point mutations in cancer are heterozygous and occur most frequently at, or closely linked to, their active sites." (PMID 35028610, 2021). "This work represents an advance in biomedical science because it shows IDH1 and IDH2 mutational spectrum, significant prevalence in large cancer series and benefit of testing them for prognosis and therapeutic management." (PMID 35996504, 2021). "Three IDH mutations (IDH1-R132x, IDH2-R172K, and IDH2-R140Q) occur predominantly in subsets of cancers and regulate central circuitry metabolism by producing the oncometabolite, 2-hydroxyglutarate (2-HG)." (PMID 34020723, 2021). "Meanwhile, genes regulating DNA methylation, including DNMT1 and DNMT3A, the TET family and IDH1 and IDH2, are themselves frequently mutated in cancer and their mutation status is associated with changes to the cancer epigenome." (PMID 34871444, 2021). "For the common mutations of IDH1 and IDH2 found in cancer, intracellular and extracellular R-2-HG levels are substantially increased." (PMID 35028610, 2021). "Preclinical studies in vitro and in vivo have shown that inhibition of mutated IDH2 enzyme can reduce the level of intracellular 2-HG, reverse the loss of epigenetic control, and release the differentiation block of cancer cells." (PMID 33981605, 2021). "In the remaining cancer types in which IDH1 or IDH2 mutations are reported, the incidence rates are lower (<5%)." (PMID 35028610, 2021). "This review will focus on the biological roles of IDH2 mutation in tumorigenesis, and provide a proof-of-principle for the development and application of IDH2 mutant inhibitors for human cancer treatment." (PMID 33981605, 2021). "In this review, we discuss the biological roles and therapeutic applications of IDH2 mutations in human cancers." (PMID 33981605, 2021). "Prognostic variants were identified in or near MSH6, POLQ, ARID5B, and IDH2, which are previously reported cancer driver genes." (PMID 32066500, 2020). "IDH1 and IDH2 genes are frequently mutated in some tumors and represent the metabolic genes most frequently mutated in human cancers." (PMID 32859092, 2020). "Many studies provide evidence that oncogenes can alter cancer cell metabolism including glutamine transporters which were associated with high IDH2 in this study." (PMID 31599393, 2020). "Frequent mutations in the IDH1 and IDH2 genes have been shown in different types of cancer, including CCA." (PMID 32138158, 2020). "Mutated forms of IDH2 are associated with cancer, in which a mutant enzyme acquires the ability to produce the oncometabolite 2-oxoglutarate instead of αKG20." (PMID 32015410, 2020).
cancer (continued). "IDH1 and IDH2 have been found mutated in multiple human cancers, rendering them as promising targets for anti-cancer therapy." (PMID 33114695, 2020). "Apart from some common cancer mutations that were highly enriched (like missense mutations in IDH2 or excess synonymous mutations in MP2K1), the team found strong negative selection acting on the majority missense and nonsense mutations." (PMID 33115454, 2020). "In contrast, a small molecule-binding pocket in the IDH2 oncogene is recurrently mutated across cancers, and, thus, it is readily detected using interaction tracks alone but is less significantly ranked when PertInInt is restricted to other functionality data." (PMID 32711844, 2020). "Links have been established between the patient's IDH1 or IDH2 mutation pattern, molecular mechanisms of the alternated epigenetic niche, and reprogrammed metabolism for predicting prognoses for various cancers." (PMID 31847543, 2020). "IDH1 and IDH2, that produce α-ketoglutarate, can be present in mutated forms in many different kinds of cancers." (PMID 32328088, 2020). "Isocitrate dehydrogenase 1 and 2 (IDH1 and IDH2) are two of the most frequently mutated metabolic genes in human cancer." (PMID 34766113, 2020). "Recent advances in cancer genetics have found mutations in the isocitrate dehydrogenase 1 (IDH1) and 2 (IDH2) genes occur frequently in a variety of human cancers, including AML." (PMID 33409153, 2020). "The discovery of IDH1 and IDH2 mutations in several malignancies has brought to the approval of drugs targeting IDH1/2 mutants in cancers." (PMID 31010244, 2019). "Mutations in IDH1 and IDH2 are found in different cancer types including brain tumor (over 70% of gliomas), colorectal cancer, prostate cancer and hematological malignancies as AML and myelodysplastic syndromes." (PMID 31234353, 2019). "Hotspot mutations in IDH1 and IDH2 have subsequently been shown to occur in at least 13 types of cancer, including 70% of malignant gliomas, 30% of AML and 5–25% of cholangiocarcinomas." (PMID 31795195, 2019). "Acquisition of hotspot mutations in IDH1 and IDH2 are key events in the development of various types of cancer." (PMID 31139406, 2019). "Among these genes, NGFR, PRKN, STAT3, IDH2, etc. were associated with the neuronal system and cancer pathway as the significant terms (P < 0.001)." (PMID 31708732, 2019). "Many studies support that IDH2 deficiency promotes several diseases, including cancer, ischemia-reperfusion injury, inflammation, and age-related spinal deformities." (PMID 31503005, 2019). "In these patients, similar to cancer, IDH2 mutation leads to the production and accumulation of D-2-HG in the presence of functional D2HDH, which results in an even higher urinary excretion of D-2-HG compared to patients with D-2-HGA type I20." (PMID 31092874, 2019). "Cancer genomic analyses have identified that an abnormal increase in the D-2HG level is associated with mutations in either IDH1 or IDH2." (PMID 31221981, 2019). "For LGG, we further adjusted for cancer subtype defined based on the IDH1 or IDH2 mutation and chromosome 1p and 19q co-deletion." (PMID 30388102, 2018). "For example, the isocitrate dehydrogenase enzymes IDH1 and IDH2 function as RBPs [19•, 20••], and are strongly linked to cancer." (PMID 29216518, 2018). "Our findings have broad implications for the roles of IDH2 mutations in aging and cancer: First, a complete loss of IDH2 likely leads to hearing loss in older adults." (PMID 29567975, 2018). "Neomorphic mutation R140Q in the metabolic enzyme isocitrate dehydrogenase 2 (IDH2) is found to be a driver mutation in cancers." (PMID 29184081, 2017). "IDH1 and IDH2 mutations are also responsible for hypermethylation, decreased differentiation, and increased stemness of cancer cells as well as HIF-1α-mediated angiogenesis and growth of tumour." (PMID 28373964, 2017).
cancer (continued). "Based on that; in certain tumors, IDH1 R132 and IDH2 R172 mutations are considered as driver ones, emphasizing the importance of targeting them as a cancer treatment therapy in those tumors." (PMID 28785398, 2017). "Isocitrate dehydrogenase 1 and 2 (IDH1 and IDH2) are key metabolic enzymes that are mutated in a variety of cancers to confer a gain-of-function activity resulting in the accumulation of an oncometabolite, D-2-hydroxyglutarate (2-HG)." (PMID 28986582, 2017). "In summary, the discovery of IDH1 or IDH2 mutations in human cancers has opened a window of opportunity for targeted therapies against cancers harboring these mutant enzymes." (PMID 27635066, 2016). "With the discovery of isocitrate dehydrogenase (IDH1 and IDH2) mutations in cancer and the associated accumulation of an unique de novo product, 2-hydroxyglutarate (2HG), the phrase ‘oncometabolites’ was coined." (PMID 27635066, 2016). "Nevertheless, neomorphic mutations have recently been demonstrated in isocitrate dehydrogenases 1 and 2 (IDH1 and IDH2), which are mutated in several cancer types such as glioma and AML." (PMID 26024390, 2015). "In IDH1- or IDH2-mutated cancers, the oncometabolite 2HG acts as a biomarker of compromised enzyme activity." (PMID 25632305, 2015). "It has also been shown that wild-type IDH2 expression contributes to the resistance of cancer cells to programmed cell death caused by various environmental insults, including ionizing radiation." (PMID 26703734, 2015). "Somatic heterozygous mutations in IDH1 and IDH2 have been recognized recently in a number of cancers." (PMID 23847760, 2013). "To date, all reported IDH1 or IDH2 mutations are heterozygous, with cancer cells retaining one wild-type copy of the respective IDH1 or IDH2 allele." (PMID 23847760, 2013). "The high frequency of IDH1 and IDH2 mutations in certain cancers, and the specificity of the genetic alterations to a limited set of amino acid residues, makes the mutant IDH1 or IDH2 product a tempting target for therapy." (PMID 22885298, 2012). "Based on this, IDH1 and IDH2 mutants have been proposed to inhibit the activity of the wild-type IDH1 or IDH2 allele in cancer cells in a dominant-negative fashion." (PMID 21326614, 2011). "The frequent observation of heterozygous hotspot mutations in IDH1 and IDH2 suggests that they are proto-oncogenes that are activated by these mutations in cancer." (PMID 21326614, 2011). "The fact that the gain of the enzymatic activity to produce 2HG is a shared feature of the IDH1 and IDH2 mutations suggests that this is an important function for these mutants in driving cancer pathogenesis." (PMID 21326614, 2011). "While mutations in IDH1 and IDH2 enzymes, typical producers of 2-HG in certain cancers, are rare in CRC, our findings suggest that a glycolytic phenotype may promote the 2-HG accumulation even without these mutations." (PMID 40185729, 2025). "Mutations in IDH genes, notably IDH1 and IDH2, have been extensively investigated in various cancers such as colon cancer, and these mutations may lead to alterations in cellular metabolism and epigenetic regulation, thereby contributing to tumorigenesis." (PMID 40066443, 2025). "By contrast, our study provides evidence that IDH2 deficiency may promote cancer initiation from a different perspective." (PMID 41258072, 2025). "We also include a state-of-the-art literature review about IDH1 and IDH2 molecular biology, biochemical properties, and the role of their mutations in cancer development and progression, along with insights into regional variations in cancer biology and treatment response." (PMID 40182999, 2025). "IDH1 and IDH2 mutation-related cancers are increasingly showing abnormal histone and DNA methylation, which may affect stem cell differentiation and ultimately lead to carcinogenesis." (PMID 40017726, 2025). "Based on these findings, we speculated that IDH2 deficiency in macrophages inhibits the metastatic ability of cancer." (PMID 39256649, 2024).
cancer (continued). "The IDH2 mutated cells are transcriptionally similar to monocytes, which could be either healthy or cancer." (PMID 39163479, 2024). "Moreover, we observed that colony formation was decreased in cancer cells (LLC1) co-cultured with IDH2-deficient macrophages compared to those co-cultured with WT macrophages." (PMID 39256649, 2024). "In cancer cells (LLC1) co-cultured with IDH2-deficient macrophages, the expression of E-cadherin, a cell adhesion protein, remained unchanged, whereas those of mesenchymal markers vimentin and fibronectin were decreased compared with their expressions in only cancer cells (LLC1)." (PMID 39256649, 2024). "2HG is normally present at low levels but may increase enormously when there are specific mutations in the genes encoding IDH1 or IDH2, and which are associated with several cancers including gliomas, leukemias, and renal cell carcinomas." (PMID 39057706, 2024). "The discovery that mutations in isocitrate dehydrogenases (IDH1 or IDH2) could drive cancer development due to the abnormal generation of an oncometabolite 2-hydroxyglutarate is another example of the direct involvement of altered metabolism in carcinogenesis." (PMID 38658533, 2024). "In addition to the mutated versions, wild-type IDH2 has been shown to play a role in antioxidant defense and to promote cell growth and survival of cancer cells." (PMID 36831011, 2023). "Furthermore, the identification of IDH1 and IDH2 mutations in cancer further emphasizes the direct relationship between metabolic instability and carcinogenesis." (PMID 37569414, 2023). "However, mutations in either IDH1 or IDH2 occur in many other cancers, which can be a possible susceptible target by IDH mutant vaccination." (PMID 37296846, 2023). "Mutations in IDH1 and IDH2 occur frequently in human cancers." (PMID 35269796, 2022). "A spectrum of mutations is observed at IDH1 and IDH2 in cancers." (PMID 35804976, 2022). "Overall, cancer cells harboring IDH1/IDH2 mutations display hypermethylation of DNA and histone." (PMID 35935878, 2022). "Moreover, IDH2-mutated carcinomas seem to be characterized by hypermethylation and upregulation of the repressive H3K27 epigenetic mark, opening the door for a DNA methylation-based classification of SNUC." (PMID 35059992, 2022). "In addition, FH and IDH mutations lead to tumor initiation through the repression of cellular differentiation, and IDH1 and IDH2 mutations cause an energy shift in cancer cells." (PMID 34445360, 2021). "Given the higher levels of D-2HG and its association with better survival, understanding how IDH2-R172 glioma cells overcome D-2HG induced sensitization to ferroptosis will shed light on the mechanism of IDH2-mutant gliomagenesis and the rare occurrence of such a mutation in human cancer." (PMID 34440884, 2021). "IDH mutations are generally rare in some common cancers (breast, prostate and gastric), apart from some rare sub-types such as Breast Solid Papillary carcinoma with reverse polarity, where 77% of cases have IDH2 mutations." (PMID 34854890, 2021). "Of note, mutations in IDH1 and IDH2 genes were shown to reprogram the metabolism of cancer cells to produce the onco-metabolite D-2-hydroxyglutarate and cells with mutations might be additionally dependent on lactate (see for review)." (PMID 33800955, 2021). "Mutational prevalence of IDH1 and IDH2 genes in various human cancers." (PMID 35996504, 2021). "Therefore, further study on the biological roles of IDH2 mutations in tumorigenesis and development of potent IDH2 mutant inhibitors will improve the clinical treatment of certain cancer types." (PMID 33981605, 2021). "IDH1 and IDH2 are recurrently mutated in several types of human cancer." (PMID 35996504, 2021).
cancer (continued). "Indeed, LDHA, PKM, and IDH2 are well-known players in the upregulation of cancer metabolism which are strongly associated with aggressive and invasive behavior of tumors and shortened patient’s survival." (PMID 33311447, 2020). "Gain of function mutations in IDH2 result in an increase in the oncometabolite 2-hydroxyglutarate (2-HG) which is believed to link aberrant metabolism and aberrant epigenetics and gene regulation in cancer." (PMID 31599393, 2020). "Interestingly, the expression of IDH enzymes (in particular IDH1 and IDH2) is frequently altered in multiple types of cancer, and a number of mutations have been reported too." (PMID 31504662, 2019). "Here, we evaluated the three most frequent IDH2 mutations occurring in cancer." (PMID 31105869, 2019). "Heterozygous somatic mutations in IDH1 or IDH2 genes have been detected in many cancers." (PMID 31105869, 2019). "IDH2 is a metabolism-associated gene, which might act as oncogene by promoting cancer cell metabolism and growth." (PMID 29769567, 2018). "It has been reported that IDH1 and IDH2 neomorphic mutations are prevalent in various cancers." (PMID 28827794, 2017). "IDH1 and IDH2 mutations arise early in cancer pathogenesis and are specific for hotspot codons, suggesting that these mutations have a shared oncogenic function that drives cancer pathogenesis." (PMID 21326614, 2011). "Heterozygous point mutations in IDH1 and IDH2 occur in a significant portion of human cancers." (PMID 21326614, 2011). "Also, the difference was more pronounced in condition with cancer co-culture, the reason for the increased difference may be M2-like polarization is stronger in WT macrophage compared to IDH2-deficient macrophage." (PMID 39256649, 2024). "Thus, we propose that IDH2 deficiency in macrophages is a pivotal regulator of cancer progression." (PMID 39256649, 2024). "However, the structure of Homo sapiens IDH2 and other point mutants associated with cancers remains unclear." (PMID 36335201, 2022). "Interestingly, mutations only in IDH1 and IDH2 have thus far been linked to cancer." (PMID 27196610, 2016). "In addition, it was shown that IDH1 or IDH2 mutations could also result in the reduction of 5hmC in cancers." (PMID 26366235, 2015). "By structural and functional analysis, IDH1 and IDH2 mutated cells gained the neomorphic enzymatic activity creating a condition with 2HG oncometabolite accumulation which promotes tumorigenesis through inhibiting a cancer-associated transcription factor such as hypoxia-induced factor (HIF)." (PMID 22397365, 2012). "In addition, this type of mutation may contribute to tumorigenesis and provide a protective mechanism in cancers that possess IDH2 mutations." (PMID 23226729, 2012). "In mutant IDH2-expressing cancer models, such cells demonstrate increased ATP production through OXPHOS and suppressed glycolytic flux, particularly under hypoxic conditions." (PMID 40724998, 2025). "In contrast, ENO3, IDH2, IDH3G, and MDH2, genes that encode proteins that generally represses the proliferative, migratory, and invasive capacities of cancer cells, displayed the strongest positive correlations across nearly all cancers." (PMID 40806276, 2025). "Research on solid tumours, a pan-cancer analysis, has demonstrated that IDH1 mutations occur more frequently and affect a broader range of cancer types compared to IDH2." (PMID 40182999, 2025). "Meanwhile, KEGG and GO analyses showed that IDH2 was involved in the glyoxylate metabolic process, glutathione metabolism, and central carbon metabolism in cancer which were related to mitochondrial homeostasis." (PMID 39587987, 2025). "IDH2 is ubiquitously expressed across many cancers, with significant upregulation observed in tumors like ACC, LGG, and GBM." (PMID 40282990, 2025).